CA11 (carbonic anhydrase 11 (inactive))
Description:
Does not have a catalytic activity.
Synonyms: CA-XI; CA-RP II; CARP-2; CARP2; CARPX1; CA-RP
Tractability: Small molecule: a high-quality ligand is known; it belongs to a druggable protein family. Antibody: UniProt places it where antibodies can reach, with high confidence; UniProt predicts a signal peptide or a membrane-spanning region; its Gene Ontology location is reachable by antibodies, with medium confidence. PROTAC: a small molecule that binds it is known.
Target class: Enzyme
Gene: Protein-coding gene on chromosome 19 (48,637,946 to 48,646,386, reverse strand). Ensembl gene ENSG00000063180.
Subcellular location: Secreted
Subcellular location (Human Protein Atlas): Microtubules; Vesicles; Predicted to be secreted
Gene Ontology:
Molecular function: carbonate dehydratase activity; neurexin family protein binding; zinc ion binding
Cellular component: basolateral plasma membrane; extracellular region
Genetic constraint (gnomAD): Loss-of-function variants: 17 observed, 37.58 expected, observed/expected ratio (o/e) 0.45, 90% interval 0.31 to 0.68. The upper end of that interval is the gene's LOEUF score, 0.68, which puts it in group 2 of 6, group 1 being the genes least tolerant of losing a copy. Missense variants: 315 observed, 417.75 expected, observed/expected ratio (o/e) 0.75, 90% interval 0.69 to 0.83. Synonymous variants: 161 observed, 173.56 expected, observed/expected ratio (o/e) 0.93, 90% interval 0.81 to 1.06.
Homologues: Orthologues: chimpanzee CA11 (100% identical), pig CA11 (98% identical), macaque CA11 (97% identical), rat Car11 (97% identical), mouse Car11 (97% identical), guinea pig CA11 (94% identical), dog CA11 (91% identical), tropical clawed frog ca11 (59% identical), Drosophila melanogaster CARPB (36% identical), Caenorhabditis elegans cah-1 (30% identical), zebrafish ca2 (25% identical), zebrafish cahz (25% identical), and 12 more. Paralogues in human: CA10 (53% identical), CA2 (27% identical), CA13 (26% identical), CA7 (26% identical), CA5A (25% identical), CA5B (25% identical), CA8 (25% identical), CA3 (24% identical), CA1 (23% identical), CA12 (23% identical), CA9 (23% identical), CA14 (22% identical), and 2 more.
Diseases named in the same sentence as CA11 in open-access papers:
CA11 is named in the same sentence as 15 diseases in open-access papers, as found by Europe PMC text mining. Sharing a sentence is not in itself a finding about the gene and the disease. The quoted sentences say what the papers report.
glioma (3 papers, 2017 to 2023). A benign or malignant brain and spinal cord tumor that arises from glial cells (astrocytes, oligodendrocytes, ependymal cells). "We found that CA11 reduction was associated with short survival in patients and CA11 knockdown promoted glioma aggression in various in vitro and in vivo assays." (PMID 30636076, 2019). "Carbonic anhydrase‐related proteins 11 and 10 (CA11 and CA10) are secreted synaptic proteins which function as neurexin ligands, and the gene‐encoding CA11 is part of a gene signature associated with radiotherapy and prognosis in gliomas." (PMID 30636076, 2019). "As CA11 is also expressed by glia themselves in normal brains, we further investigated the expression and function of glioma CA11." (PMID 30636076, 2019). "As CA11 is a ligand for neurexin, and glioma cells also express some types of neurotrophin receptors, it is possible that secreted CA11 binds to these receptors to modulate downstream signaling pathways." (PMID 30636076, 2019). "Consistently, qRT‐PCR result shows that CA11 mRNA levels were also reduced in gliomas compared with normal tissues, and were further reduced in high‐grade gliomas." (PMID 30636076, 2019). "To explore the potential effects of reduced CA11 expression on the behaviors of gliomas, we investigated the effects of CA11 knockdown on proliferation, clone formation, in vitro migration, apoptosis, and in vivo tumor formation in glioma cell lines." (PMID 30636076, 2019). "In contrast, CA11 immunostaining was almost lost in high‐grade gliomas." (PMID 30636076, 2019).
gastric cancer (1 paper, 2006). A primary or metastatic malignant neoplasm involving the stomach. "Both AMP-18 and the CA11 gene product have been reported to be intensively expressed in normal stomach tissue but not in most gastric cancers." (PMID 17187689, 2006).
ovarian carcinoma (1 paper, 2018). A malignant neoplasm originating from the surface ovarian epithelium. "In contrast to LAMA4, CA11, and MEDAG, the 2 mRNAs, SPINT2 and NANOG, were found to be increased in ovarian cancer ascites compared to peritoneal fluid EVs." (PMID 29499737, 2018). "Three mRNAs, CA11, LAMA4, MEDAG, were .01–.28-fold lower expressed and two mRNA, SPINT2 and NANOG, were 3.2–5.8-fold higher expressed in ovarian cancer ascites versus peritoneal fluid EVs." (PMID 29499737, 2018). "Based on previous studies relating to these mRNA, CA11 and MEDAG may be involved in maintaining malignant ascites microenvironment, while LAMA4, NANOG and SPINT2 activities could regulate ovarian cancer progression and metastasis." (PMID 29499737, 2018).
cancer (4 papers, 2014 to 2023). A tumor composed of atypical neoplastic, often pleomorphic cells that invade other tissues. "Moreover, we report, for the first time, the association of IL12RB1, CA11, CD276, and APBB1IP with cancer-associated inflammation." (PMID 37228491, 2023). "The qPCR studies identified five mRNA (CA11, MEDAG, LAMA4, SPINT2, NANOG) and six miRNA (let-7b, miR23b, miR29a, miR30d, miR205, miR720) that were significantly differentially expressed between cancer ascites and peritoneal fluids." (PMID 29499737, 2018).
tumor (2 papers, 2019 to 2021). "CA11 knockdown promoted cell growth, clone formation, and migration; inhibited apoptosis; and increased tumor size in xenografted nude mice." (PMID 30636076, 2019). "In addition, CA11 knockdown promoted aggressive tumor behaviors in various in vitro and in vivo assays." (PMID 30636076, 2019). "In addition, CA11 knockdown promotes aggressive tumor behaviors in in vitro and in vivo assays." (PMID 30636076, 2019).
gastrointestinal tumors (1 paper, 2023). "A carbonic anhydrase, CA11, was also associated with inflammation which overexpression promotes the proliferation and invasion of gastrointestinal tumors without any previous association with CRC in plasma." (PMID 37228491, 2023).
CA11 also shares sentences with these, for which no sentence is quoted: Spinocerebellar ataxia 3 (2 papers); Alzheimer disease (1); Ataxia (1); breast carcinoma (1); cervical carcinoma (1); clear cell carcinoma (1); oligodendroglial tumor (1); serous ovarian adenocarcinoma (1); Spinocerebellar ataxia type 3 (1).